TNF (tumor necrosis factor)
Diseases named in the same sentence as TNF in open-access papers (continued):
Sharing a sentence is not in itself a finding about the gene and the disease.
breast carcinoma (continued). "Breast cancer survivors who received surgery plus chemotherapy had significantly elevated levels of TNFα activity compared to those who had only surgery." (PMID 33352780, 2020). "NF-κB upregulates the target gene TRAIL, which plays a key role in TNFα-enhanced apoptosis of breast cancer cells induced by DOX." (PMID 32225068, 2020). "In MDA-MB-231 cells was demonstrated that TNF-α increased the expression profile and activity of MMP-9 by inducing JUNB DNA binding activity, thus strengthening the concept of a pro-tumorigenic effect of TNFα in breast cancer." (PMID 33187552, 2020). "Having confirmed the high concentration of TNFα in bevacizumab-resistant breast cancer and inhibition of TNFα suppressed tumor migration and IDO1 expression in vitro, we treated MDA-MB-231-bearing mice with bevacizumab, anti-TNFα nanobody, both, or PBS." (PMID 33214550, 2020). "Mast cells derived from adipose tissue promote apoptosis of breast cancer cells by secreting TNF-α and granulocyte-macrophage colony-stimulating factor." (PMID 33363026, 2020). "Reports in favor of the anti-proliferative and apoptotic effect of TNFα on luminal breast cancer have only been executed on the MCF-7 cell line." (PMID 32391269, 2020). "In this review, TNFα is not only closely involved in breast cancer onset, progression and in metastasis formation, but it also participates by favoring therapy resistance." (PMID 32391269, 2020). "TNFα mRNA and protein were present in malignant and stromal cells in biopsies of breast cancer patients, and especially in those with worse prognosis." (PMID 32391269, 2020). "In order to investigate how exercise in breast cancer affects inflammatory cytokines, IL-6, IL-18, TNF-α, and CRP mRNA expression levels were analyzed in the livers of the study mice." (PMID 32309219, 2020). "The role of TNF-α-308 G/A and TNF-β +252 A/G gene polymorphism in the etiology of breast cancer (BC) is not clearly understood." (PMID 32102503, 2020). "Although there are several reports showing TNFα participation in aromatase induction (described in the luminal breast cancer section), few studies have addressed its impact on aromatase inhibitors resistance." (PMID 32391269, 2020). "BT474, SKBR3, MDA-MB-453 and MDA-MB-231 breast cancer cells exhibited 1.12, 0.72, 0.01 and 0.01 fold TNF-α fold expression when normalized to β-actin expression." (PMID 33292267, 2020). "Present study was designed to investigate the association of TNF -α-308G/A (rs1800629) and TNF-β +252 A/G (rs361525) gene and their association with breast cancer in Indian population." (PMID 32102503, 2020). "Specific to TNF-α, breast cancer patients reporting increased social satisfaction or social activities had stronger TNF-α responses to an endotoxin challenge." (PMID 32116590, 2020). "Further study of the effects brazilin on TNFα signaling and PB in metastatic breast cancer cells is required." (PMID 32986377, 2020). "All this evidence provides a proof-of-concept for proposing the blockade of TNFα as a promising therapy in breast cancer." (PMID 32391269, 2020). "Firstly, it suggests recombinant TNF therapy as a potential therapy in such cancers, in particular colorectal and breast cancers." (PMID 32805626, 2020). "The results show that long-term exercise reduces TNF-α mRNA expression in breast cancer mice, and long-term running can inhibit TNF-α in the liver." (PMID 32309219, 2020).
breast carcinoma (continued). "TNF was expressed on lung cancer, head and neck cancer, stomach cancer, urothelial cancer, breast cancer, cervical cancer, endometrial cancer, and ovarian cancer." (PMID 32434423, 2020). "On the other hand, de novo trastuzumab-resistant breast cancer cell lines exhibited greater TNFα levels than the sensitive ones." (PMID 32391269, 2020). "Recombinant TNFα enhanced sensitivity of breast cancer cells to WEHI-539 and this was further enhanced in the presence of recombinant IFNα." (PMID 31937780, 2020). "In conclusion, this study suggests that AIM acts as an inhibitor of the TNF-α induced effect by the suppression of NF-κB-regulated gene expression in breast cancer cells." (PMID 32455624, 2020). "Among isoflavones, genistein and daidzein are known to inhibit TNFα-induced migration and invasion of human breast cancer cells by preventing the inhibition of NF-κB." (PMID 32708426, 2020). "TNF-α was previously shown to induce aerobic metabolism in prostate epithelial cells and glycolytic reliance in mammary carcinoma cells." (PMID 32694701, 2020). "As NF-κB is one of the main transcription factors activated by TNFα, we will here also highlight the primary data pointing out to the relationship between NF-κB and resistance to breast cancer therapies." (PMID 32391269, 2020). "Forced knockdown of SMG7 by siRNA (siSmg7) in NIH 3T3 and MCF‐7 breast cancer cells restored viability upon TNFα treatment." (PMID 32602581, 2020). "Preclinical studies performed in melanoma, lung and breast cancer show that TNFα induces expression of PD-L1." (PMID 32391269, 2020). "Several proteins from the TNF signaling pathway play important roles in breast cancer and its treatment." (PMID 32756008, 2020). "In this study, we investigated the role of the transcription factor early growth response gene 1 (EGR-1) in the induction of CYP19 expression in response to TNFα stimulation in ER-positive MCF-7 breast cancer cells." (PMID 33053908, 2020). "Myeloid expansion in the bone marrow was driven by G-CSF in the MMTV-PyMT mouse model of breast carcinoma, while it was found to be TNFα-dependent in Lewis lung carcinoma and MC57 fibrosarcoma." (PMID 33042791, 2020). "Another study demonstrated that TNFα activates mesenchymal stromal cells that leads to metastasis in breast cancer through the recruitment of CXCR2+ neutrophils." (PMID 32986377, 2020). "KEGG pathway enrichment analysis revealed that brazilin targets the TNF signaling pathway in inhibition of metastatic breast cancer cells." (PMID 32986377, 2020). "The serum CTLA-4, TNF-α and IL-6 levels of 57 female cats with mammary carcinoma were determined by ELISA, and immunohistochemistry was performed to evaluate CTLA-4 and FoxP3 expression in tumor cells and interstitial lymphocytes." (PMID 32123292, 2020). "Further, this study provides evidence that in the 12-week running program conducted, TNF-α mRNA expression was significantly decreased in the breast cancer exercise group compared to the breast cancer group." (PMID 32309219, 2020). "The decreased serum TNF- α level and mammary tumor volume in the Aegle marmelos treated group significantly denotes the anti-inflammatory and anti-proliferative property of the plant extract." (PMID 33093498, 2020). "Aegle marmelos treatment showed significantly reduced mammary tumor volume (P < 0.05), along with significant reduction (P < 0.0001) in the different serum biomarkers such as TNF-α level, serum malondialdehyde (MDA) level and glucose levels." (PMID 33093498, 2020). "In the present study, a significant reduction in the mammary tumor volume and serum TNF-α level was observed in Aegle marmelos treated group as compared to the DMBA treated group." (PMID 33093498, 2020).
breast carcinoma (continued). "TNF-α participates in multiple cellular signaling pathways by binding to receptors, which correlates with inflammation and survival of breast cancer." (PMID 31500658, 2019). "We have previously shown that breast cancer cellular sensitivity to TNF death ligands is correlated with the corresponding death receptor (DR) expression on the plasma membrane." (PMID 30650534, 2019). "The results confirmed that TNF-α induces upregulation of CCL2 expression in both breast cancer cell lines and IL-6 expression in MDA-MB-231 cells." (PMID 31665136, 2019). "In breast cancer patient samples, TNF-α serum concentration was related to poor prognostic and metastasis development." (PMID 31137684, 2019). "In this study, co-culture of conditioned macrophages and breast cancer cells resulted in strong, sustained increase of TNF-α and IL-6 protein levels." (PMID 30736340, 2019). "Interaction between macrophages and ERα+ breast cancer cells in a proinflammatory microenvironment favors expression of TNF-α and IL-6." (PMID 30736340, 2019). "It is interesting to consider these studies in light of our findings that only secretomes from metastatic Py230 breast cancer cells decrease pro-inflammatory TNFα while maintaining CD73 in the lung." (PMID 31105883, 2019). "In breast cancer, high concentrations of TNF-α can activate receptors and trigger a potent and persistent activation of NFқB signaling, epithelial-to-mesenchymal transition, and continuous release of diverse chemokines, including CCL2 and CCL5." (PMID 31665136, 2019). "Rac3 depletion in invasive MDA-MB-231 breast cancer cells strongly reduces invasion and increases Tumor Necrosis Factor (TNF)-induced apoptosis, supporting a role for Rac3 in the aggressiveness of these tumor cells." (PMID 31514269, 2019). "We realized a decreased expression of IKKα, p-p65/NF-κB, and TNF-α in both breast cancer cells which correlated with decreased PTX3 expression." (PMID 30740360, 2019). "We have previously shown that SWF from patients treated by IORT significantly stimulates the apoptotic pathway in the luminal A subtype of breast cancer cells by activating the TNF-induced extrinsic apoptotic pathway." (PMID 31861498, 2019). "Here, by using the TCGA breast cancer dataset we found that TNFα and IL-1β were expressed in significantly higher levels in basal tumors than in luminal-A tumors (Figures 1A1,B1)." (PMID 31031757, 2019). "It has been reported that lncRNA NKILA activates NF-κB signaling in MDA-MB-231 breast cancer cells by stimulating up-regulation, such as TNF-α or lipopolysaccharide (LPS)." (PMID 31383786, 2019). "In the present study, we found OA-suppressed cell proliferation, migration, invasion, and EMT phenotype formation were promoted by TNF-α, leading to aggravation of breast cancer process, which is consistent with previous reports." (PMID 31341911, 2019). "Our results suggest that methylation of the RELA gene contributes to expression of NF-κB1 in response to TNF-α in breast cancer." (PMID 31382678, 2019). "On the other hand, TNF-α combined with radiotherapy or cryosurgery results in a synergistic antitumor response or complete tumor destruction, respectively, in breast cancer models." (PMID 31093512, 2019). "Intriguingly, both early and late estrogen response genes were upregulated in granulocytes treated with TNF-α, and macrophages, despite reports that TNF-α acts to oppose estrogen signaling in breast cancer." (PMID 31263060, 2019). "In particular, interleukin-1β (IL-1β) and tumor necrosis factor-α (TNF-α) proinflammatory cytokines have an important role in the interaction between breast cancer cells and their microenvironment." (PMID 31093512, 2019). "The role of IL‐6 and TNF‐α in the adhesion, migration, and apoptosis of breast cancer cells has attracted more and more attention." (PMID 31762993, 2019).
breast carcinoma (continued). "A recent study showed that serum IL-6, IL-8, and TNF-α were positively correlated with clinical tumor stage and lymph node status in Chinese breast cancer patients." (PMID 31430979, 2019). "It has been described that melatonin, in co-cultures of human breast cancer cells and 3T3-L1 fibroblasts, decreases the levels of TNFα, IL-11, and IL-6 in the culture media and downregulates TNFα, IL-11, and IL-6 mRNA expression in both types of cells." (PMID 31412584, 2019). "Other studies have also reported the presence of cytokine co-expression such as tumor necrosis factor alpha (TNFα) expression with IL-6 to have a prognostic significance in breast cancer." (PMID 31007849, 2019). "Present results revealed a marked increase of TNF-α concentration in 4 T1 breast cancer bearing mice challenged with a combination of NDV AF2240 and tamoxifen." (PMID 30947706, 2019). "It has been demonstrated that calcitriol and its analogues improve the antiproliferative response of therapeutic agents and potentiate TNF-α-induced cytotoxicity on breast cancer cells." (PMID 31093512, 2019). "Despite the epidemiological evidence, there are no published trials regarding the effects of vitamin D supplementation on blood levels of 25 (OH)D, TNF-α, TGF-β1, and TAC in accordance with the different variation of VDR polymorphism among breast cancer women." (PMID 31350967, 2019). "In a similar way, in this study, we demonstrated that the combination of calcitriol with TNF-α resulted in a greater antiproliferative effect than drug alone in all breast cancer cells evaluated." (PMID 31093512, 2019). "Pitavastatin has shown its potential modulatory effects on NFκB activation, activated by TNF-α, in a breast carcinoma cell line." (PMID 31330988, 2019). "Here, we underscore the role of IAPs in the mechanism by which CORT and DEX interfere with the TNF-mediated cytotoxic effect on MCF7 breast cancer cells." (PMID 30987626, 2019). "Visfatin shows antiapoptotic properties in TNF-α-induced apoptosis in breast cancer cells and palmitate-induced apoptosis in pancreatic β-cells." (PMID 31772700, 2019). "IFN-γ and/or TNF-α primed adipose-derived MSCs (AD-MSCs) reduced E-cadherin expression in breast cancer cell line MCF-7 via elevated TGF-β1 signaling." (PMID 31130595, 2019). "In conclusion, we found that the level of the RELA gene methylation was significantly related to the levels of NF-κB1 transcripts in breast cancer with positive expression of TNF-α." (PMID 31382678, 2019). "We showed that Dec1 expression is induced by HIF-1α in oral cancer cells under hypoxia, by TNFα in breast cancer cells under apoptosis, and by TGFβ1/pSmad3 in epithelial–mesenchymal transition of pancreatic cancer cells." (PMID 31597354, 2019). "TNF-α enhances the fusion of breast cancer cells and epithelial cells by upregulating the expression of MMP-9 in cancer or epithelial cells." (PMID 31380426, 2019). "Many studies have shown that TNF-α-induced autophagic cell death occurs in various cancer cell types including breast cancer, hepatoma and ovarian cancer." (PMID 31540489, 2019). "Our current findings demonstrate that TNFα induces GM-CSF in MDA-MB-231 breast cancer metastatic cells." (PMID 31581558, 2019). "Another study showed that TNF-α can promote transendothelial migration of breast cancer via upregulation of LOX." (PMID 31341911, 2019). "Breast cancer cell lines co-cultured with TNF-α-conditioned macrophages were used as pro-inflammatory tumor microenvironment models." (PMID 30736340, 2019). "The contents of β-ABA exhibited the highest average correlation to inhibition of TNF-α, IL-6, and IL-8 cytokine release as well as cytotoxicity against breast cancer cells." (PMID 31581678, 2019).
breast carcinoma (continued). "Here, decreased expression of PTX3 post rBmK AGAP treatment correlated with decreased IKKα, p65/NF-κB, TNF-α, and NF-κB DNA binding and transcription activity inhibiting breast cancer cell stemness and epithelial-mesenchymal transition." (PMID 30740360, 2019). "In contrast, antagonist of PPARγ inhibits breast cancer cell growth and increases E2-induced apoptosis via regulation of oxidative stress and NF-κB-dependent TNFα expression." (PMID 31815253, 2019). "This study showed that TNF enhances proliferation of breast cancer cells via the activation of p42/p44 mitogen-activated protein kinases (MAPK) pathway by binding to both TNFR2 and TNFR1." (PMID 31239840, 2019). "Glucocorticoid (GC)-dependent protection against tumor necrosis factor (TNF)-induced cell death has been well characterized in MCF7 luminal A breast cancer cells." (PMID 30987626, 2019). "In our in vitro experiments, we found that TNF-mediated cytotoxicity is inhibited by GCs (CORT or DEX) in MCF7 breast cancer cells." (PMID 30987626, 2019). "Administering CDK4/6 for treating breast cancer has been reported to increase TNF-α production and antigen presentation." (PMID 30828336, 2019). "Once knockdown of RIP3, the effect of TNF-α strengthening the cytotoxicity of 5-FU in breast cancer cells was abolished." (PMID 31739592, 2019). "An anti-TNF-α nanobody was able to reduce TNF-mediated proliferation and migration potency of breast cancer cell lines." (PMID 31544819, 2019). "The PERK/NF-κB/TNFα axis is identified as the key drive to induce apoptosis after E2 treatment of LTED breast cancer cells." (PMID 31815253, 2019). "The MCF7 cell line is the only breast cancer cell line reported to have a cytotoxic response to TNF." (PMID 30987626, 2019). "In contrast to these findings in breast cancer cells, studies have also shown that TNF-α can inhibit YAP." (PMID 31083564, 2019). "In the context of cancer, NLRX1 plays a role in TNF induced mitochondria-lysosomal crosstalk in mammary tumors." (PMID 31681307, 2019). "All of these findings suggest that PERK is a key regulator to convey stress signals from the endoplasmic reticulum to the nucleus and illustrate a crucial role for the novel PERK/STAT3/NF-κB/TNFα axis in E2-induced apoptosis in E2-deprived breast cancer cells." (PMID 29531812, 2018). "In another study, CD47 expression in breast cancer cells was shown to be enhanced by the TNF-NF-κB1 inflammatory pathway, and its inhibition by blocking antibodies increased the recruitment of the innate immune system and phagocytosis." (PMID 30213113, 2018). "We recently demonstrated that the fusion of human M13SV1-Cre breast epithelial cells and human MDA-MB-435-pFDR1 breast cancer cells under normoxic and hypoxic conditions is positively triggered by TNF-α." (PMID 29636110, 2018). "It does so, in part, by regulating production of GM-CSF, IL1α, IL-6, and TNFα by breast cancer cells." (PMID 29593211, 2018). "More recently, it was reported that Chi3l1 by fibroblast enhances migration and growth of breast cancer, and knockdown of Chi3l1 by shRNA increases T cell population and IFNy, TNFα expression." (PMID 29403003, 2018). "In this study, the expressions of TNFα, NF-κB p50 subunit, and IL-4 were related to specific clinicopathologic characteristics in breast cancer." (PMID 29315254, 2018). "The complex pathophysiology that exists between adipose tissue, inflammation and breast cancer involves inflammatory mediators (i.e., IL-6 and TNF-α) that enhances tumor progression and survival." (PMID 30619088, 2018). "TNFα, another ubiquitous TME cytokine, regulates expression of genes associated with metastatic phenotypes in ERα-positive breast cancer cells." (PMID 29463044, 2018). "For example, hyperthermia using a water bath was shown to sensitize breast cancer cells to bortezomid or TNF (Tumor Necrosis Factor), resulting in enhanced cell death." (PMID 29954075, 2018).